TMEM62 (transmembrane protein 62)
Synonyms: FLJ23375
Tractability: Antibody: UniProt predicts a signal peptide or a membrane-spanning region. PROTAC: its protein half-life has been measured.
Gene: Protein-coding gene on chromosome 15 (43,123,279 to 43,185,144, forward strand). Ensembl gene ENSG00000137842.
Subcellular location: Membrane
Subcellular location (Human Protein Atlas): Cytoplasmic bodies; Nuclear bodies; Nucleoli fibrillar center; Nucleoplasm
Gene Ontology:
Molecular function: protein binding; hydrolase activity
Cellular component: membrane
Genetic constraint (gnomAD): Loss-of-function variants: 28 observed, 52.08 expected, observed/expected ratio (o/e) 0.54, 90% interval 0.4 to 0.74. The upper end of that interval is the gene's LOEUF score, 0.74, which puts it in group 3 of 6, group 1 being the genes least tolerant of losing a copy. Missense variants: 593 observed, 653.75 expected, observed/expected ratio (o/e) 0.91, 90% interval 0.85 to 0.97. Synonymous variants: 235 observed, 242.37 expected, observed/expected ratio (o/e) 0.97, 90% interval 0.87 to 1.08.
Homologues: Orthologues: chimpanzee TMEM62 (99% identical), macaque TMEM62 (97% identical), dog TMEM62 (88% identical), guinea pig TMEM62 (87% identical), pig TMEM62 (86% identical), rabbit TMEM62 (84% identical), mouse Tmem62 (83% identical), rat Tmem62 (83% identical), tropical clawed frog tmem62 (57% identical), zebrafish tmem62 (34% identical).
Diseases named in the same sentence as TMEM62 in open-access papers:
TMEM62 is named in the same sentence as 4 diseases in open-access papers, as found by Europe PMC text mining. Sharing a sentence is not in itself a finding about the gene and the disease. The quoted sentences say what the papers report.
ovarian carcinoma (1 paper, 2022). A malignant neoplasm originating from the surface ovarian epithelium. "Increased TMEM62 expression led to decreased proliferation of ovarian cancer cells in vitro and decreased tumor burden in vivo." (PMID 36077735, 2022).
tumor (3 papers, 2019 to 2022). "In vivo analysis using the OVCAR8-TMEM62-TetON model showed decreased tumor burden in mice with high- vs. low-expressing TMEM62 tumors." (PMID 36077735, 2022). "Senescence has been associated with a tumor suppressive process, inhibiting tumor growth, decreasing proliferation and even increase the chance of immune related events for tumor clearance, which may explain the mechanism by which TMEM62 could affect long-term survival." (PMID 36077735, 2022). "To determine whether the overexpression of TMEM62 affects tumor growth and progression, we developed a TetOn system cell line model using OVCAR8 cells." (PMID 36077735, 2022). "There were also genes that are of insignificant expression in tumor cells that increase in expression in KO cells, e.g. THBS3, IL2RG, SPRR3, TGM2, HMOX1 and TMEM62 or are lower in expression in tumor cells and significantly decreased in KO cells such as MAN1A1, CES1, STCBP6, SIVA1 and TMEM40." (PMID 31797958, 2019).
TMEM62 also shares sentences with these, for which no sentence is quoted: cancer (1 paper); serous ovarian carcinoma (1).